HERC5 (HECT and RLD domain containing E3 ubiquitin protein ligase 5)
Diseases named in the same sentence as HERC5 in open-access papers (continued):
Sharing a sentence is not in itself a finding about the gene and the disease.
infection (34 papers, 2011 to 2025). The state of being infected such as from the introduction of a foreign agent such as serum, vaccine, antigenic substance or organism. "Although EBOV VP24 and VP35 can act broadly to dampen the IFN response, several IFN-induced antiviral proteins, including HERC5, are also highly upregulated early in response to other stimuli associated with infection, such as pro-inflammatory cytokines." (PMID 34572049, 2021). "HERC5 was shown to exhibit antiviral activity towards ssRNA viruses such as HIV-1 and dsDNA viruses such as HPV, of which infection has been shown to increase risk of SjD development regardless of age." (PMID 40565345, 2025). "Included in this set are critical genes like ISG15 and HERC5, indicating a potentially universal defense tactic early in infection." (PMID 39591472, 2024). "The E3 ubiquitin ligase HERC5 was significantly upregulated upon ASFV-10L-GFP infection at the mRNA and protein level." (PMID 37417777, 2023). "Important next steps will be to characterize the mechanism of GP antagonism and to test the importance of this HERC5-GP axis early in infection using animal models." (PMID 34572049, 2021). "Among the top genes with the strongest early increases in expression after infection in vivo is IFN-induced HERC5." (PMID 34572049, 2021). "In this review, we examine the emerging role of ISG15 in antiviral immunity with a particular focus on how HERC5 orchestrates the specific and timely ISGylation of viral proteins in response to infection." (PMID 34207696, 2021). "HERC5 inhibited the replication of HIV-1 over multiple rounds of infection and was found to target a late stage of HIV-1 particle production." (PMID 22093708, 2011). "Taken together, these data show that HERC5 expression is significantly increased in patients in the acute and chronic stages of infection and in patients in stages of long-term control of infection." (PMID 22093708, 2011). "In accord with this, depletion of endogenous Ube1L from the Huh7.25.CD81 cells, as such or after ectopic expression of ISG15, UbcH8 and HERC5, resulted in an increase in IFNβ induction after infection with HCV." (PMID 22022264, 2011). "These genes contribute to the regulation of iron metabolism (FTH1), modification of proteins in response to infection (HERC5), presentation of antigens to the immune system (MAMU-AG), control of apoptotic pathways (IFI6 and PLAC8), and direct antiviral activities." (PMID 40742121, 2025). "In contrast to ISG15 null cells, we did not observe differences between WT and HERC5-deficient cells when we evaluated both foci area and number of infected cells per foci following infection with DV." (PMID 38384473, 2024). "In addition, the number of genomic copies and TCID50 after ASFV-10L-GFP infection revealed that the replication of ASFV was significantly weakened after HERC5 knockdown compared to the control siRNA groups." (PMID 37417777, 2023). "The upregulation of ISG15, ISG20, ISG15 family ligases (HERC5/6), and ISG15 proteases (USP18) also appeared upon infection, which has been reported to participate in host antiviral immunity." (PMID 37752509, 2023). "In the presence of HO infection, the stimulatory effect of IFNT on expression of GBP4, ISG15, HERC5, RSAD2, IFIH1, IFIT3, and MX1 was significantly reduced (IFNT vs. IFNT+HO, P < 0.05–0.01)." (PMID 33898551, 2021). "Infection with either HO or KY alone had similar inhibitory effects on most ISGs (ISG15, GBP4, HERC5, RSAD2, DDX58, and IFIT3), although a slightly greater inhibitory effect of HO was observed on IFI27 and MX1." (PMID 33898551, 2021). "The stimulatory effect of IFNT on RSAD2, IFIT3 and MX1 was inhibited to a greater extent by HO infection and only HO inhibited GBP4 and HERC5 expression." (PMID 33898551, 2021). "To address the antiviral properties of mHerC6 in mouse cells, we determined if HerC5/6 expression would confer antiviral resistance to VSV-GFP and NDV-GFP infection." (PMID 22272257, 2012).
infection (continued). "PHEV significantly upregulated ISG15 expression (>1.5 log2FC) at all three time points, and it appears ISG15 does interact with HERC5, IFIT1, PKR, TRIM25, STAT1, and USP18, as their expression was also enhanced (>1.0 log2FC) at various timepoints during ALI-PRECs infection." (PMID 38932231, 2024). "RNA interference of UBE1L (E1), UbcH8 (E2), Herc5 (E3), and UBP43 (ISG15 protease) revealed that ISGylation inhibits HCMV growth by downregulating viral gene expression and virion release in a manner that is more prominent at low multiplicity of infection." (PMID 27564865, 2016). "Given the notion that newly synthesized proteins are targeted extremely broadly, perhaps stochastically, by Herc5 in polyribosomes, several other HCMV proteins may be ISGylated during infection." (PMID 27564865, 2016). "Moreover, we showed that EBOV (Zaire) glycoprotein (GP) but not Marburg virus GP antagonized HERC5 early during infection." (PMID 34572049, 2021). "In the PRV- and mock-infected groups, 241 differentially expressed proteins (DEPs) were identified, 162 upregulated and 79 downregulated proteins at 24 h post-infection (hpi), among which AFP, Vtn, Hsp40, Herc5, and Mccc1 may play important roles in PRV propagation." (PMID 34680952, 2021). "A recent report indicated that HerC5 mainly conjugates ISG15 to newly synthesized proteins in tissue culture and may by that mechanism largely target de novo synthesized viral proteins during infection." (PMID 22272257, 2012). "Pretreatment of cells did not prevent subsequent infection with Neospora (not shown), but blocked Neospora induction of the antiviral genes IRF7 and HERC5, 3-fold and 4-fold, respectively." (PMID 24505488, 2014).
cancer (11 papers, 2014 to 2024). A tumor composed of atypical neoplastic, often pleomorphic cells that invade other tissues. "In summary, loss of HERC5 leads to a metabolic switch, which is one of the hallmarks of cancer; this switch favors the suppression of normal oxidative phosphorylation (OXPHOS) and the adaptation to hypoxia." (PMID 38605423, 2024). "A number of enzymes involved in the ISGylation process, namely E3 ligases (HERC5 and EFP/TRIM25) and USP18 have been shown to be associated with cancers via ISGylation-dependent and -independent mechanisms 15-18." (PMID 32132870, 2020). "The nine mRNAs are coding for proteins involved in cell cycle regulation (CDCA7L), modification of the T cell and B cell immune response (GBP2, GLUL, HERC5, PPP3CC), erythropoiesis (GBP2), and cell migration of cancer and hematopoietic cells (HERC5, HMHA1)." (PMID 28236054, 2017). "The function of HERC5 in cancer is closely related to ISGylation, and the study of the role of HERC5 in cancer might be in coincidence with the change in ISGylation level." (PMID 36771004, 2023). "This implies that HERC5 may serve as important regulator during the development of cancer therapy resistance." (PMID 33375322, 2020). "For example, apart from its antiviral role, some evidences suggest that HERC5 might be functionally involved in other pathways, such as spermatogenesis and cell cycle, as well as cancer." (PMID 33391270, 2020). "In addition, there were multiple genes induced that are involved with cell and organelle structure and function (PNCK, UBD, CDH2, HERC5) and importantly, genes associated with the prostate, AR (MMP7, CDH2, ENO2, IGFBP3) and cancer (IFIT3, IFI44L)." (PMID 29416764, 2018). "Because it is known that expression of all proteins from this system is INF dependent, it could be suspected that HERC5 should also be increased in these cancers." (PMID 29027969, 2017). "In contrast, increased expression of the S100A3 and HERC5 genes was described in different cancers." (PMID 29027969, 2017). "On the other hand, in NSCLC cancer, HERC5 downregulation correlates with poor survival." (PMID 29027969, 2017).
tumor (9 papers, 2015 to 2024). "On the molecular level, these studies showed that HERC5 loss could drive immunosuppression and tumor progression." (PMID 38605423, 2024). "Thus host anti-viral responses are activated by the presence of HERC5 and reduced by its absence, suggesting an association with regulation of innate immune responses, a potential critical function leading to tumor recurrence in HCC." (PMID 26653219, 2015). "Furthermore, in several different tumor entities, HERC5 mRNA expression, often as part of a signature, has been correlated with diagnostic and prognostic characteristics in different tumor entities, indicating a potentially important role of HERC5 in metastasis." (PMID 38605423, 2024). "Based on these results, we analyzed the effect of HERC5 depletion on tumor cell dissemination and metastasis outgrowth in a mouse model in more detail." (PMID 38605423, 2024). "We previously showed that low HERC5 expression predicts early tumor dissemination and a dismal prognosis in NSCLC patients." (PMID 38605423, 2024). "To further investigate the role of HERC5 in tumor cell dissemination and survival in distant tissues, we first carried out in vivo experiments in a zebrafish model." (PMID 38605423, 2024). "Here, we showed that the dissemination of tumor cells is increased in HERC5 KO cells in comparison to that in their parental counterpart, causing an increase mainly in the adrenal gland and brain metastases." (PMID 38605423, 2024). "Previously, we and others have identified tumor and metastasis suppressive functions of HERC5 in different tumor entities." (PMID 38605423, 2024). "The E3 ligase activities of HERC5 have been identified in a variety of biological processes, such as protein degradation, cell signaling, tumor suppression, and antiviral defense." (PMID 36834974, 2023). "We found that protein levels of HERC5 were down-regulated in GS-treated cells and the central region of tumor, this trend inversely correlated with the expression of 4EBP1." (PMID 36575176, 2022). "HERC5 plays a crucial role in HCC immune evasion and has clinical relevance as a reproducible prognostic marker for risk of tumor recurrence and survival in patients." (PMID 26653219, 2015). "HERC5 was also identified as a prognostic biomarker for both survival and tumor recurrence in HCC patients in three independent HCC patient cohorts." (PMID 26653219, 2015). "From this analysis, the following genes were identified: NAA11, HERC5, DDX60, and HERC6 which were evaluated individually for association with tumor recurrence using the 21 Chinese patient primary tumors." (PMID 26653219, 2015). "Additionally, in hepatocellular and colorectal cancer, low HERC5 expression was correlated with shorter tumor recurrence and OS." (PMID 38605423, 2024). "Thus, HERC5 downregulation is responsible for metastasis formation in vivo, leading to earlier and more aggressive tumor dissemination." (PMID 38605423, 2024). "In this study, we used an integrated omics strategy to identify a hemizygous DNA deletion and concordant mRNA under-expression of HERC5, an IFN-induced HECT-type E3 protein ligase gene associated with shorter: time to tumor recurrence and overall survival in HCC patients." (PMID 26653219, 2015). "Expression of EFP, HERC5 and UBA1 in non-tumour tissues were positively correlated with direct bilirubin levels (Spearman's rho =0.31, 0.33 and 0.45; P=0.06, 0.05 and 0.01, respectively)." (PMID 32132870, 2020). "Expression of EFP, HERC5, UBA1, and USP18 was significantly higher in HCC tumour tissues compared to the adjacent non-tumour tissues (P=0.006, 0.012, 0.02 and 0.039, respectively)." (PMID 32132870, 2020). "In non-tumour tissues, EFP expression was strongly correlated with that of HERC5, UBA1 and USP18 (Spearman's rho =0.81, 0.89 and 0.75; P<0.0001, respectively)." (PMID 32132870, 2020).
tumor (continued). "Relative expression of the five genes EFP, HERC5, UBA1, UBC and USP18, which are related to ISGylation, was quantified and compared between HCC tumour and adjacent non-tumour tissues." (PMID 32132870, 2020). "Overexpression of HERC5, downregulation of CtBP1, or blockade of CtBP1 function with its inhibitors (NSC95397 and 4-methylthio-2-oxobutyric acid [MTOB]) significantly prevents CRC cell proliferation in vitro and tumor growth in vivo." (PMID 36771004, 2023). "In line with a previous study 18, we also observed upregulation of HERC5 in HCC tumour tissues and a correlation of HERC5 expression with direct bilirubin levels in non-tumour tissues." (PMID 32132870, 2020). "Thus, the expression of HERC5 and other parts of the ISG15 protein degradation system seems to be tumor type specific." (PMID 29027969, 2017). "Unfortunately in this study, HERC5 DNA loss was only evaluated in the 4 HCC patients with matched primary and recurrent tumor specimens, since DNA sequencing was not conducted on the remaining 17 HCC patients." (PMID 26653219, 2015). "Here we show that expression of E3 ligases (HERC5 and EFP/TRIM25), UBA1 and USP18 is significantly upregulated in HCC tumours compared to adjacent non-tumour liver tissues." (PMID 32132870, 2020). "The upregulation of EFP, HERC5, UBA1 and USP18 in HCC tissues and the different patterns of correlation of the genes in HCC tumour and in adjacent non-tumour tissues suggest that these genes may play a role in the pathogenesis of HCC." (PMID 32132870, 2020). "In addition, HERC5 and CCL20 mRNAs were significantly negatively correlated (p = 0.0003) in the PTs of HCC patients who experienced tumor recurrence and not in the PTs of HCC patients who did not experience tumor recurrence (p = 0.49)." (PMID 26653219, 2015).
bacterial infection (2 papers, 2019 to 2022). "In our study, the expression of IFI44 and HERC5 were found to be up-regulated that means host system tried to resist bacterial infection." (PMID 31749827, 2019).
HERC5 also shares sentences with these, for which no sentence is quoted: adenocarcinoma (2 papers); Gestational Diabetes Mellitus (2); influenza (2); non-small cell lung carcinoma (2); Alzheimer disease (1); Autoimmunity (1); Azoospermia (1); bovine respiratory disease complex (1); Cirrhosis (1); cutaneous melanoma (1); glioblastoma (1); H1N1 virus infection (1); Hepatitis (1); leukaemia (1); lipidosis (1); measles (1); Nephropathy (1); neutropenia (1); osteosarcoma (1); parasite infection (1); pterygium (1); renal cell carcinoma (1); sterility (1); stomach adenocarcinoma (1); triple-negative breast carcinoma (1); urothelial bladder carcinoma (1).